NANOG (Nanog homeobox)
Diseases named in the same sentence as NANOG in open-access papers (continued):
Sharing a sentence is not in itself a finding about the gene and the disease.
melanoma (30 papers, 2011 to 2025). A malignant, usually aggressive tumor composed of atypical, neoplastic melanocytes. "To understand the underlying mechanism of NANOG-driven resistance to PD-1 blockade, we first assessed the transcriptomes of TCGA melanoma patients with varying NANOG signature expression." (PMID 35104240, 2022). "NANOG and Oct4 overexpression is correlated with increase invasiveness of human melanoma cell lines and NANOG up-regulation is associated with worse prognosis and survival in cutaneous melanoma." (PMID 35847038, 2022). "Concomitant with the Lunasin-induced phenotypic shift, we observed a significant reduction in the expression of NANOG, a transcription factor implicated in migration, invasion, self-renewal, and dedifferentiation of melanoma cells." (PMID 27566591, 2016). "Additionally, this subpopulation of melanoma cells expressed high levels of the stem-cell-associated markers Oct-4 and NANOG." (PMID 27566591, 2016). "Additionally, Lunasin-treated ALDHhigh cells from both A375 and SKMEL-28 melanoma lines showed reduced expression of the stem-cell-associated transcription factor, NANOG." (PMID 27566591, 2016). "Mechanistic studies revealed that Lunasin treatment of isolated melanoma CICs induced expression of the melanocyte-associated differentiation markers Tyrosinase and Microphthalmia-associated Transcription Factor concomitant with reduced expression of the stemness factor NANOG." (PMID 27566591, 2016). "The investigation revealed that SUZ12, SOX2, TCF3, NANOG and SMAD4 are the maximum chief TFs that control the largest number of genes associated with metastatic-melanoma." (PMID 39820173, 2025). "NANOG expression was positive in 30 cases (60%) of primary melanoma, with a median H-Score of 15 and with increased expression observed in cases with pagetoid migration and lesions in situ." (PMID 39459448, 2024). "An analysis of the H-Score for the immunohistochemical reaction with anti-NANOG antibodies in the group of patients with melanoma metastases (n = 10) determined that eight cases were positive and two cases were negative." (PMID 39459448, 2024). "Of note, nests of stem-like melanoma cells have been identified in metastatic lesions in head and neck cancer patients and shown to express NANOG, OCT4, SOX2, KLF4, and cMYC." (PMID 37270599, 2023). "In melanoma, melanosphere formation correlates with increased expression of NANOG which induces the transcription of genes regulating motility and tissue transmigration as well as favours SNAIL-1-mediated activation of the key genes involved in EMT." (PMID 36291854, 2022). "We observed that transient forced-increase of RKIP expression in metastatic melanoma cells led to the decrease of NANOG promoter activation pointing towards a functional relationship among RKIP and NANOG expression." (PMID 32503139, 2020). "Although stemness features have been attributed to melanoma, our evaluation of stemness genes (NANOG, POU5F1, PROM1 and SOX2), revealed a very low expression among the tested cells on 2D culture." (PMID 32230715, 2020). "The specific regulatory pathways affected by Lunasin to effect MITF and NANOG expression in melanoma ALDHhigh cells remain to be identified." (PMID 27566591, 2016). "We also observed increased expression of OCT4 and NANOG when naïve cells were exposed to the secretome of melanoma cells rendered senescent by the chemotherapy drugs." (PMID 24344100, 2013). "Interestingly, OCT3/4, NANOG and Klf4 mRNAs were up-regulated by 680C91, suggesting a critical role of stem cell markers in regulating melanoma cell malignancies." (PMID 38794128, 2024). "The results of our study regarding the expression of CD133 and NANOG markers in melanoma, both in cases of primary cutaneous melanoma and at the level of local recurrences and metastases, provide valuable information on the importance of these molecules in the activity of tumor stem cells." (PMID 39459448, 2024).
melanoma (continued). "Furthermore, post-translational regulation of RKIP in melanoma involves mir-21, one of the targets of NANOG and EMT." (PMID 36291854, 2022). "Interestingly, melanospheres derived from dex-stimulated parental (adherent) melanoma cells displayed a remarkable increase in stem cell markers (Oct3/4, AP-1, E2f1, Sox2 and NANOG), and that this increase was TDO-mediated." (PMID 35847038, 2022). "Melanoma stem cells, in particular, are characterized by the expression of embryonic transcription factors, including NANOG (Homeobox protein), Oct4 (octamer-binding transcription factor 4) and Sox2 (sex-determining region Y HMG-box 2)." (PMID 35847038, 2022). "In melanoma, melanosphere formation has been found to increase NANOG expression." (PMID 32503139, 2020). "Therefore, according to the similar behavior of CDH5 and NANOG in our melanoma culture model, we evaluated their relationship in tumor sections." (PMID 32230715, 2020). "On the other hand, enforced expression of TAF4 promoted expression of pluripotency- associated KLF4, OCT4 and NANOG, and NC-related MSX2, PAX7, SOX10 and SNAI1, reaffirming the critical role of hTAF4-TAFH activity in the maintaining of multipotency in melanoma cells." (PMID 27499390, 2016). "The ALDHhigh melanoma cancer cell subpopulation has been reported to harbor the tumor-initiating and metastatic cells that express several self-renewal stemness genes including NANOG." (PMID 27566591, 2016). "Mechanistically, RKIP acts primarily as tumour suppressor also in melanoma, in fact, its silencing results in increased expression of various oncogenes (KIT, BCL3, MAF, MYC, MYCL, HOXA9, CDC25B, and PIM1), most of which are associated with the transcription factor NANOG." (PMID 36291854, 2022). "Five hub genes including CXCL11, ICAM1, LEF1, MITF, and STAT1 were identified, SUZ12, SOX2, TCF3, NANOG, and SMAD4 were determined as the most significant TFs in metastatic-melanoma." (PMID 39820173, 2025). "TCGA dataset revealed that TIPE has a positive relationship with CSCs markers, including BMI1, NANOG, NOTCH1, and POU5F1 in melanoma." (PMID 39728923, 2024). "Lastly, TCGA dataset revealed that TIPE has a positive relationship with CSCs markers including BMI1, NANOG, NOTCH1, and POU5F1 in melanoma." (PMID 39728923, 2024). "miR-21 is a known target for NANOG and an important inducer of EMT affecting migration and invasion capability suggesting a possible role for this onco-miRNA in melanoma malignancy." (PMID 32503139, 2020). "First, we confirmed a significant induction of stemness NANOG, POU5F1 and PROM1 in the melanoma sphere formation process, in both primary and secondary WT spheres." (PMID 32230715, 2020). "Here, we showed that the secretome of senescent melanoma cells drives basal melanoma cells towards a mesenchymal phenotype, with characteristic of stems illustrated by increased level of the prototype genes FN1, SNAIL, OCT4 and NANOG." (PMID 24344100, 2013). "Expression of NANOG and Cripto-1, the co-receptor of NODAL that acts as mediator of cell fate in embryological and adult systems, was detected in aggressive melanoma." (PMID 21526207, 2011). "Indeed, melanoma-specific CD133+ isolated cancer stem cells exhibit increased stem cell markers, such as NANOG and Oct3/4, and possess tumor-initiating potential, compared to CD133- cells." (PMID 35847038, 2022). "Moreover, we analyzed the expression levels of KLF4, NANOG, OCT3/4, and CD271, which are genes involved in stemness features and are able to induce pluripotency in melanoma." (PMID 34298765, 2021). "Moreover, NANOG and OCT4 overexpression increases motility and transmigration of melanoma cells." (PMID 32503139, 2020). "Indeed, melanoma CSC can be identified because they display either undifferentiation or embryonic state markers, such as NGF receptor, Prominin-1 (CD133), Transcription Factor Sox2, Octamer-binding protein 4, and Homeobox protein NANOG (NANOG)." (PMID 31783660, 2019).
melanoma (continued). "Expression of OCT4 or transmembrane delivery of OCT4 protein promotes dedifferentiation of melanoma cells to CS/IC-like cells possessing an increased tumorsphere-formation capacity, an enhanced tumorigenic capacity and increased expression levels of endogenous OCT4, NANOG and KLF4." (PMID 28768501, 2017). "Furthermore, in a study conducted on CD133 + transgenic mice and human melanoma cells, promotion of neovascularisation in tumour microenvironment was induced by the Sox10 high expression, along with that of organic cation transporter (OCT) 3/4 and Nanog homeobox (Nanog)." (PMID 35334544, 2022).
cervical carcinoma (29 papers, 2013 to 2025). A carcinoma arising from either the exocervical squamous epithelium or the endocervical glandular epithelium. "They suggested that the stromal cytoplasmic NANOG staining was associated with the progression of cervical cancer." (PMID 38558704, 2024). "A substantial body of literature indicates a strong association between the malignant phenotype of cervical cancer cells, including cancer stem cells, and the altered expression of STAT3 and NANOG." (PMID 40729003, 2025). "Our results support the idea of the usefulness of the chemosensitisation of cancer cells using molecular targeting, especially in reference to the connection between STAT3/NANOG activation in the cervical cancer HeLa cell model." (PMID 40729003, 2025). "Our data agree with previous reports in which C-MYC activities are down-modulated in pancreatic CSC, while Noh and colleagues showed enrichment of stem-cell phenotypes in human cervical cancer cells by NANOG upregulation." (PMID 32764385, 2020). "NANOG has been reported in cervical epithelial lesions and rectal cancer as well as in a group of patients with radioresistant cervical cancer where NANOG was in nucleus; in another study, NANOG induced tumorigenesis in vivo." (PMID 31885625, 2019). "The expression of OCT4, SOX2, and NANOG in cancer stem cell-enriched cultures of HeLa, SiHa, and CaSki cell lines from cervical cancer was higher than their conventional cultures in monolayer." (PMID 31885625, 2019). "A previous report demonstrated that knockdown of STAT3 protein in cervical carcinoma cell line by siRNA reduced mRNA and protein expressions of NANOG and SOX2." (PMID 29963272, 2018). "Lymph node metastatic cervical cancer cells utilize FAO-derived acetyl Co-A to increase histone H3K27 acetylation at the promoters of stemness genes, as well as enhance the expression of pluripotency-related transcription factors (SOX2, OCT4, and NANOG) and the cervical cancer stem cell marker CD44." (PMID 41219902, 2025). "Another study demonstrated that the overexpression of INO80 and NANOG could promote cervical cancer cell proliferation and tumorigenesis." (PMID 38020889, 2023). "Interestingly, according to the IHC study, in cervical cancer cells and surrounding stromal cells, NANOG was frequently observed in the cytoplasm, instead of the nucleus, where it is found in many other cell types." (PMID 27343550, 2017). "Importantly, FGF2 expression was positively correlated with expression of API5 and NANOG in cervical cancer tissue, validating the biochemical pathway that we proposed." (PMID 28092370, 2017). "Finally, expression of the stem cell self-renewal-associated transcription factors OCT4, NANOG, KLF4 and BMI1 is elevated in ALDHhigh cervical cancer cells." (PMID 24318570, 2013). "The cytoplasmic NANOG that is expressed in stromal cells may promote cervical cancer progression." (PMID 27343550, 2017). "Ectopic PIWIL1 overexpression in cervical cancer cells promotes tumor sphere formation by regulating the stem cell-related transcription factors OCT4, NANOG, KLF4, and BMI1, thus conferring resistance to cisplatin." (PMID 35083142, 2021). "In cervical cancer, a combined determination of the markers ALDH, OCT4, and NANOG is recommended; the activity of ALDHA1 and OCT4 is increased in the tissues of cervical cancer and precancerous lesions, as well as in the blood plasma." (PMID 34830452, 2021). "High risk human papillomavirus (HR-HPV) promotes self-renewal by upregulating OCT-3/4, NANOG, and SOX2 expression to maintain the cervical cancer stem cell (CCSC) in the cervical cancer." (PMID 32178477, 2020). "It has been reported that some oncogenes and transcription factors are correlated with cervical cancer and likely involved in the development and progression of cervical cancer, such as SOX2, KLF4, OCT4 and NANOG." (PMID 28514765, 2017). "In addition, other transcription factors such as NANOG, OCT4, LGR5, and EZH2 promote tumor formation in cervical cancer." (PMID 33947962, 2021).
cervical carcinoma (continued). "We analyzed their expression using RT-qPCR and found that OCT4, SOX2, and NANOG are overexpressed in CSC-enriched sphere cultures as compared with same cell lines grown under adherent conditions from HeLa and SiHa cell lines derived from cervical cancer." (PMID 31885625, 2019). "The level of expression of OCT4, SOX2, KLF4, C-MYC, and NANOG (OSKM-N) proteins was higher in cervical cancer (CC) samples than in a nontumor sample." (PMID 31885625, 2019). "Also, overexpression of FAP1-AS1 had no statistical impact on cervical cancer cell stemness, as shown by no statistical difference in the level of NANOG and SOX2 between the control group and the overexpressed AFAP1-AS1 group." (PMID 39574469, 2024). "To investigate potential targets for impeding NANOG-driven autophagy in cisplatin-resistant tumor cells, we compared the expression of genes involved in EGFR hyperactivation among the genes upregulated by NANOG and highly expressed in chemotherapy-resistant cervical cancer patients." (PMID 37165076, 2023).
colorectal cancer (28 papers, 2013 to 2025). A primary or metastatic malignant neoplasm that affects the colon or rectum. "In the clinical samples, high levels of ZFP57 were shown to be positively associated with NANOG expression, as well as nodal and liver metastasis in colorectal cancer." (PMID 37492743, 2023). "NANOG has been reported to act as a tumor marker in patients with colorectal cancer and is associated with clinical and pathological features." (PMID 37047234, 2023). "Mechanistically, we establish that NR5A2 transcriptionally activates NANOG to potentiate stemness in colorectal cancer (CRC) cells—a previously unreported regulatory axis." (PMID 41214698, 2025). "NR5A2 was identified as a key therapeutic target in colorectal cancer (CRC) through a dual mechanism involving the regulation of NANOG." (PMID 41214698, 2025). "Especially, overexpression of NANOG has been found to predict tumor progression and poor prognosis in colorectal cancer." (PMID 38233377, 2024). "A study by Xu and colleagues on colorectal cancer also showed that higher NANOG-expression correlated with more frequent postoperative liver metastases." (PMID 37492743, 2023). "Stemness-associated genes NANOG, OCT3/4 and SOX2 are involved in self-renewal activity of colorectal cancer cells." (PMID 27314328, 2016). "Overexpression of NANOG protein has been previously found in a variety of tumors, including breast cancer, colorectal cancer, gastric carcinoma and OSCC." (PMID 24348816, 2014). "In human colorectal cancer, NANOG modulates stemness and tumorigenicity." (PMID 37047234, 2023). "Importantly, NANOG induces the dormancy, migration, and chemoresistance of colorectal cancer cells." (PMID 38468952, 2024). "NANOG inhibition could result in suppression of cell proliferation in colorectal cancer cell lines." (PMID 37461005, 2023). "NANOG overexpression could be observed as a factor for poorer patient survival in several tumor entities, for instance in gastric adenocarcinoma as well as in colorectal cancer." (PMID 37461005, 2023). "It has been also documented that the overexpression of NANOG as an oncogene along with OCT4 is a prominent characteristic of CSCs and is associated with EMT transition of CSCs and drives tumor progression and poor prognosis in patients with breast and colorectal cancer." (PMID 33849536, 2021). "In colorectal cancer, EMT and stemness maintenance were controlled simultaneously by inducing the IGF/STAT3/NANOG/Slug axis." (PMID 37660003, 2023). "RNAi-mediated silencing of NANOG expression suppressed proliferation and increased apoptosis in the EpCAM+/CD44+ CSC population of HCT116 colorectal cancer cells." (PMID 37047234, 2023). "Spheroid culture from the HT-29 cell line, a more realistic colorectal cancer in vitro model, shows significantly higher expression of ABCG2, NANOG, SOX2 and POU5F1 compared to 2D cell culture conditions." (PMID 37445716, 2023). "In colorectal carcinoma, TFAP2C enhances the expression of stemness-related factors, such as Nanog homeobox (NANOG), BMI1 proto-oncogene (BMI-1), POU class 5 homeobox 1 (OCT4) and SRY-Box transcription factor (SOX2), and the phenotypes of cancer stem cells." (PMID 37291585, 2023). "We found that CCNP increases spheroid formation in breast, lung and colorectal cancers, and upregulates the expression of stemness (CD44, CD133) and pluripotency (SOX2, OCT4, NANOG) markers." (PMID 34604945, 2021). "Furthermore, the TIC phenotype in colorectal cancer can be regulated by an extracellular insulin-like growth factor (IGF) signaling pathway, which regulates NANOG via STAT3 phosphorylation." (PMID 36118530, 2022).
colorectal cancer (continued). "Sphere-derived CSCs of colorectal cancer (HCT116-SDCSCs) express significantly higher levels of stemness marker genes, for example, 4.5-fold higher levels of OCT4 and 3.2-fold higher levels of NANOG compared with those of the parental cells." (PMID 32051483, 2020). "Brachyury, a member of the T-box gene family, induces stemness markers such as NANOG, CD133, CD166, and CD44 in a colorectal cancer cell line by regulating the β-catenin oncogene and contributing to the epithelial-to-mesenchymal transition (EMT) that mediates invasion by tumor cells and metastasis." (PMID 33447348, 2020). "NANOG protein has been reported to be important in various tumor types, including OSCC (50% of primary foci and 66.7% of metastatic foci express NANOG protein), colorectal cancer (20% of tumors) and gastric carcinoma (10% of tumors)." (PMID 24348816, 2014). "Since the three pluripotent genes NANOG, OCT4, and c-MYC were hypermethylated in colorectal carcinoma HCT116 cells, we asked whether the same pattern of methylation would be observed in the rare putative CSC population in HCT116 cells." (PMID 24023739, 2013).